PAQR4 (progestin and adipoQ receptor family member 4)
Diseases named in the same sentence as PAQR4 in open-access papers (continued):
Sharing a sentence is not in itself a finding about the gene and the disease.
tumor (6 papers, 2020 to 2025). "PAQR4 is involved in immune regulation of the tumor environment, causing tumors to develop toward different immune subtypes." (PMID 36573110, 2022). "Thus, PAQR4 is associated with various biomarkers of the tumor microenvironment and has the potential to be a tumor immunotherapy target." (PMID 36573110, 2022). "All these results strongly suggested that PAQR4 might act as a risk factor for tumor progression." (PMID 36481756, 2022). "Since PAQR4 was identified recently as a novel tumour suppressor, we analysed its expression, even though it is not a recognised progesterone receptor." (PMID 39464509, 2024). "IHC staining of a total of 108 pairs of clinical HCC tissues demonstrated that the expression of PAQR4 was significantly increased in tumor tissues." (PMID 36609413, 2023). "The data from The Cancer Genome Atlas (TCGA) database indicated that the PAQR4 level was significantly increased in tumor tissues." (PMID 36609413, 2023). "The tumor weight and tumor volume in the PAQR4 overexpression group were substantially higher than those in the control group in the subcutaneous xenograft model." (PMID 36609413, 2023). "Remarkably, the expression of PAQR4 increased with the progression of tumor stage in BLCA, KIRC, KIRP, and LIHC." (PMID 36481756, 2022). "Previous studies on PAQR4 have shown that it promotes tumor metastasis, which directly affects patient prognosis." (PMID 36573110, 2022). "Our study also showed that PAQR4 had the potential value as a marker to differentiate tumor immune subtypes and guide precision therapy." (PMID 36481756, 2022). "Transcriptomic data from different sources were analyzed at the tissue and cellular levels to understand the differences in PAQR4 expression between tumor and normal groups." (PMID 36573110, 2022). "Macrophages M0 positively correlated with PAQR4 expression in tumors, it has been documented that Macrophages M0 polarized to M2 type macrophages promote tumor progression." (PMID 36481756, 2022). "TMB in seven tumor types significantly positively correlated with PAQR4 expression, and MSI of 10 types of tumors was significantly correlated with PAQR4 expression, including a significant negative correlation in DLBC." (PMID 36573110, 2022). "High levels of PAQR4 in BLCA, KIRC, KIRP, and LIHC were associated with relatively poorer tumor stages (BLCA, LIHC, P-value <0.05; KIRC, KIRP, P-value <0.001)." (PMID 36481756, 2022). "As expected, tumor formation, tumor weights and volumes in PAQR4 knockdown groups were dramatically decreased over the control group." (PMID 32206121, 2020). "To test the potential roles of PAQR4 in vivo, we performed a xenograft tumor formation assay using nude mice." (PMID 32206121, 2020). "Based on our existing data, we concluded that PAQR4 may exert its tumor-promoting effects by activating the AKT pathway in HCC." (PMID 36609413, 2023). "Interestingly, our study showed that a higher expression level of PAQR4 was detected in HCC tumor tissues than in the adjacent normal tissues in the diethylnitrosamine (DEN)-induced mouse model." (PMID 36609413, 2023). "We found different PAQR4 expression levels of different immune subtypes within the same tumor." (PMID 36573110, 2022). "A key role for PAQR4 in tumor development has been demonstrated." (PMID 36573110, 2022). "Finally, we explored the role of PAQR4 in tumor drug resistance and found that PAQR4 expression affected the sensitivity to multiple chemotherapeutic agents." (PMID 36573110, 2022). "This study elucidated the role of PAQR4 in carcinogenesis as well as tumor immunity." (PMID 36481756, 2022). "First, we investigated PAQR4 expression levels in different tumor cell lines." (PMID 36573110, 2022). "The findings above show that PAQR4 is related to immune subtypes and may regulate the tumor-immune environment." (PMID 36573110, 2022).
tumor (continued). "PAQR4 may regulate the distribution as well as the ratio of different cell subpopulations in the immune microenvironment and contribute to changes in tumor purity." (PMID 36573110, 2022). "We also correlated PAQR4 expression with the ESTIMATE score in the tumor microenvironment and found that stromal, immunological, and ESTIMATE scores were negatively correlated with PAQR4 expression in more than 3/4 of tumors, which was consistent with our previous analysis." (PMID 36573110, 2022). "Based on this data, we speculate that PAQR4 regulates tumorigenesis at the epigenetic level and further influences tumor progression." (PMID 36573110, 2022). "The poor prognosis of PAQR4 high-expression tumor patients might be due to anti-tumor immunity restricted by the enrichment of Treg and Mo macrophages." (PMID 36481756, 2022). "Although we concluded that PAQR4 can influence tumor progression through the immune environment, the exact regulatory mechanisms remain unclear, and there remain multiple avenues for PAQR4 research." (PMID 36573110, 2022). "In the remaining 16 tumors, the higher the PAQR4 expression, the higher the tumor purity." (PMID 36573110, 2022). "Furthermore, we explored the differences in PAQR4 expression between tumor and normal tissues." (PMID 36573110, 2022). "CDK4 might be another key factor in PAQR4-mediated tumor progression." (PMID 36481756, 2022). "Additionally, the relationship between PAQR4 expression and tumor purity was examined." (PMID 36573110, 2022). "Expression of mRNA encoding PAQR7 and PAQR8 in a panel of OC cell lines was below the qPCR detection limit and was downregulated in tumour tissue samples, whereas high expression of PGRMC1 and PAQR4 mRNA was observed in rare subtypes of OC cell lines." (PMID 39464509, 2024). "An antagonistic crosstalk between PAQR4 and SKP2 regulates the homeostatic level of CDK4, which promotes cell proliferation and tumor regulation." (PMID 36573110, 2022). "To further detect the pancancer PAQR4 expression level, we analyzed the TCGA RNA sequencing data using the TIMER website and found high PAQR4 expression in 17 tumor types." (PMID 36573110, 2022).
PAQR4 also shares sentences with these, for which no sentence is quoted: lung carcinoma (2 papers); lung squamous cell carcinoma (2); ovarian carcinoma (2); acute myeloid leukemia (1); esophageal carcinoma (1); gastric cancer (1); glioma (1); hepatocellular carcinoma (1); metastasis (1); pancreatic adenocarcinoma (1); paraganglioma (1); pheochromocytoma (1); prostate adenocarcinoma (1); rectum adenocarcinoma (1); renal clear cell carcinoma (1); renal papillary cell carcinoma (1); skin cutaneous melanoma (1); small cell lung carcinoma (1); thyroid carcinoma (1); uterine corpus endometrial carcinoma (1).